KITLG (KIT ligand)
Diseases named in the same sentence as KITLG in open-access papers (continued):
Sharing a sentence is not in itself a finding about the gene and the disease.
tumor (continued). "Gene expression profile analysis of multiple tumour types identified SCF (c-kit ligand) as a candidate tumour factor involved in MDSC accumulation." (PMID 22778767, 2012). "Hypoxia in the tumor microenvironment induces KITLG secretion furthering neovascularisation and promoting tumor sustenance." (PMID 22672386, 2012). "We also show that the two isoforms of the KIT ligand SCF are present in nearly all GISTs, and are produced by tumour cells." (PMID 16570044, 2006). "The elevated KITLG expression in the tumor microenvironment’s fibroblasts and endothelial cells may activate MCs through the KITLG-KIT axis, potentially suppressing tumor progression." (PMID 38031173, 2023). "The authors further hypothesize that tumor-produced stem cell factor (SCF), a c-Kit ligand, maintains mitochondrial metabolism via the c-Kit–SCF axis." (PMID 36081497, 2022). "High expressions of BRD8, TRAF3, and KITLG were related to hyperfunction of receptors in tumor or immune cell populations, which could in turn influence the survival of patients." (PMID 33790969, 2021). "To gain more insight into the mobilization of HPCs, we analyzed the expression of genes that regulate HPC maintenance and attraction in the bone marrow (CXCL12, c-kit ligand, angiopoietin-1, vascular cell adhesion molecule-1 and osteopontin) in tumor-bearing mice." (PMID 33603745, 2020). "Since imatinib preferentially targets mutant receptors, reduced drug responsiveness and aggressive GIST behavior may also reflect activation of WT KIT expressed in the majority of GIST by KITLG originating from the circulation, the tumor cells, or their niche." (PMID 24116170, 2013). "Upon activation, we observed altered transcription of KITLG, TGFB1, IFNG, SPP1, IL17A and PDCD1, whose associated functions and expression pattern marked and improved OS of BrC patients, supporting that MCs contribute with a tumor stroma with anti-tumoral functions in BrC." (PMID 32722549, 2020). "Conversely, some genes, including CXCR4, KITLG, STAT3, and TNFSF10, were downregulated, suggesting a potential suppression of specific pathways related to tumor proliferation and vascular development." (PMID 39861616, 2025). "Simultaneously, differentiation- and immune-activating signals such as CSF1, TNFSF9, KITLG, EHF, and CHRM1 were downregulated, potentially modulating tumor immune escape and proliferation in a context-dependent manner." (PMID 41009714, 2025). "Most of the 313 new disease links belonged to the DisGeNET class neoplasms (n = 40; EGFR, ERBB2, KITLG, AREG) but also to immune diseases (n = 29; FAS), neurological diseases (n = 13; PNPLA6), and cardiovascular diseases (n = 13; CD163)." (PMID 40593564, 2025). "In pursuit of comprehending the effects of KIT ligand (KITLG) on the development of TNBC in vivo, a xenograft experiment entailing subcutaneous tumor grafting was conducted." (PMID 38213737, 2024). "Correlation analysis of six prognostic MDGs (ABCG1, KDF1, KITLG, TGFA, HAVCR2, and CD14) and six types of immune infiltrating cells, including tumor purity, B cells, CD8+T cells, CD4+T cells, macrophages, neutrophils, and dendritic cells was performed." (PMID 35774505, 2022). "The considerable CXCL1-induced up-regulation of TLR4, TNFSF10/TRAIL, and KITLG expression along with MICA/MHCI down-regulation, enable tumor evasion from immune surveillance." (PMID 34195201, 2021). "Several of these genes, including KITLG, CCL14, and CKLF, are cytokines, which possibly provide a mechanism for gene dysregulation in tumor cells to affect the immune phenotype." (PMID 31480259, 2019). "One tumor expressed high levels of the KIT ligand, stem cell factor (SCF) in stromal cells within the solid component." (PMID 25941796, 2015). "Tumors from RSV-treated mice showed increased miR-34c and decreased KITLG expression, accompanied by reduced IL-6 levels, suggesting that RSV may disrupt IL-6-driven tumor progression." (PMID 40969596, 2025).
tumor (continued). "Additionally, RSV consistently inhibits epithelial–mesenchymal transition (EMT), a key process in tumor invasion and metastasis, by targeting regulatory axes such as miR-200c/EPM5 and miR-34c/KITLG." (PMID 40969596, 2025). "Likewise, the presence of KITLG and CXCL12 in Dox-EVs aligns with pathways involved in stem cell niche activation and tumor–stromal crosstalk." (PMID 40943445, 2025). "We also identified that elevated expression of KITLG (SCF) in the TME by fibroblasts and endothelial cells may activate MCs via the KITLG-KIT axis, potentially inhibiting tumor progression." (PMID 38031173, 2023). "For instance, elevating KITLG expression in fibroblasts and endothelial cells could stimulate MC activation and proliferation through the KITLG/KIT pathway, thereby inhibiting tumor cells and enhancing patient outcomes." (PMID 38031173, 2023). "The results found that the expression levels of ABCG1, HAVCR2, CD14, and TGFA were significantly increased (p < 0.05) in tumor tissue samples compared with para-cancerous control tissue samples, while the expression levels of KDF1 and KITLG were significantly decreased (p < 0.05)." (PMID 35774505, 2022). "These cells may activate MCs through the KITLG–KIT axis, potentially suppressing tumor progression." (PMID 41425713, 2025). "It is for this reason that we cannot draw conclusions regarding the comparatively higher KITLG CNV of animals with and without this tumor from the same breed." (PMID 36851392, 2023). "Moreover, although the relevance of KITLG has not been defined in GBM, the upregulation found in GBM low-responder cells might be linked to the drug resistance of these cells as has been reported in other tumor pathologies." (PMID 34316686, 2020).
cancer (133 papers, 2006 to 2026). A tumor composed of atypical neoplastic, often pleomorphic cells that invade other tissues. "Interest in KITLG has been bolstered by work showing that aberrant expression of KITLG has been implicated in the development of several cancers." (PMID 25213795, 2014). "KITLG is also known as stem cell factor, steel factor, and mast cell growth factor, whose aberrant expression has been implicated in the development of several cancers." (PMID 35774505, 2022). "However, these cells maintain active the same VEGFA-activated pathways by the upregulation of others alternative TRK receptor ligands (i.e. FGF2, PDGFD and KITLG) that have been implicated in the development and drug resistance in other cancer types." (PMID 34316686, 2020). "To delineate KITLG's function in cancer progression, we stably enhanced the expression of KITLG in MDA-MB-231 cells via lentiviral infestation." (PMID 38213737, 2024). "For instance, studies indicate that in nasopharyngeal carcinoma, KITLG potentially orchestrates the proliferation, invasion, and metastasis of cancer cells both in vitro and in vivo, via the JAK/STAT signaling pathway." (PMID 38213737, 2024). "Recent investigations suggest that KITLG inhibits cancer through the induction and Amplification of multiple signaling pathways." (PMID 38213737, 2024). "KIT proto‐oncogene ligand (KITLG) is a pleiotropic factor which is found in diverse cancers and is involved in cell proliferation, differentiation, and survival." (PMID 32463597, 2020). "Hematopoietic stem cells (HSCs) also upregulate MMP-9 to release soluble kit-ligand, also known as stem cell factor (SCF), which promotes survival signaling and chemoresistance in many types of cancers." (PMID 31334229, 2019). "Numerous cytokines have been implicated in the expansion of MDSCs during cancer progression, including G-CSF, GM-CSF, and stem-cell factor (SCF or KIT ligand)." (PMID 26500653, 2015). "The KEGG pathways that were enriched with potential miR-34c targets (enrichment score = 2.15) were cancer related (P = 0.015), and KITLG was one of the most likely targets within these pathways in cancer." (PMID 25213795, 2014). "25–27 reported that CRC tissues over-express KITLG, which is required for cancer cell growth, migration and invasion." (PMID 25213795, 2014). "The second loss on human chromosome 12 is a peak region encompassing five genes, of which one, KITLG, is listed as a putatively cancer related gene." (PMID 20735817, 2010). "Notably, the expression pattern, diagnostic, and prognostic relevance of KITLG in TNBC remains unexplored, underlining the potential significance of investigating KITLG's association with this specific cancer type." (PMID 38213737, 2024). "Evidence suggests that KITLG performs an essential role in numerous cancers." (PMID 38213737, 2024). "In addition, Adhesion G Protein-Coupled Receptor G1 (ADGRD1) functions in cell matrix adhesion and cancer progression [reviewed in 52], and KITLG (SCF/c-Kit) encodes the cytokine that acts as the ligand for the tyrosine-kinase KIT receptor." (PMID 37276213, 2023). "In our study, KITLG exon 6 alternative splicing was investigated in five cancer cell lines." (PMID 28728573, 2017). "SPRY4 is involved in the KITLG-KIT pathway, which has been associated with cancer." (PMID 23091610, 2012).
cancer (continued). "This phenomenon is exemplified here for two private cases: PAX7, a homeodomain transcription factor that plays important roles during fetal development and cancer growth, and KITLG, a ligand of the KIT tyrosine-kinase receptor, which acts in cellular development." (PMID 22096567, 2011). "Further exploration of AS modulation, specifically targeting SPAT or distinct KITLG isoforms, as a potential therapeutic strategy holds promise not only for LUAD but also for a broad range of cancer types." (PMID 40781225, 2025). "Significantly downregulated pathways found with KITLG were hematopoietic cell lineage, melanogenesis, Rap1 signaling, mitogen-activated protein kinase (MAPK) signaling, P13/AKT signaling, pathways in cancer, PLD signaling, and Ras signaling." (PMID 33575478, 2021). "Hsa_circ_0002375, hsa_circ_0111974, and hsa_circ_0081534 are spliced from KIT ligand (KITLG), estrogen related receptor gamma (ESRRG), and EPH receptor B4 (EPHB4), respectively, which play an essential role in cancer proliferation, metastasis and apoptosis." (PMID 32426279, 2020). "This resistance mechanism likely involves support by the cancer stroma since stem cell factor (SCF), the KIT ligand, is produced specifically in the stroma of resistant cancer cells with KIT amplification." (PMID 25888090, 2015). "Another hub gene, such as KITLG, PTGS2, SYK, FLT1 (VEGFR-1), GNA13, etc. could also regulate invasion and metastasis of cancer 42-48." (PMID 32194783, 2020). "Our findings suggest that, since RBM10 levels are increased in many cancers, RBM10 may be a potential therapeutic target for those cancers harbouring elevated KITLG (such as many SCLCs)." (PMID 28728573, 2017). "The selective expression of KITLG by bTAM is intriguing in view of its function as a stemness-promoting factor and the previous identification of its receptor CD133 as a marker for ovarian epithelial stem cells in the mouse and for cancer stem cells in ascites." (PMID 29141914, 2018). "In addition, we speculate that ADAM33 is involved with the KIT oncogene pathway in cancer, given that the ADAM33 catalytic domain is capable of cleaving SCF (Kit ligand) in vitro." (PMID 19267929, 2009). "The potential translational significance of these findings is that GSK3i may allow the stimulation of KITLG expression e.g. in patients with ICC loss without concomitant activation of the pathways that mediate IGF1’s actions promoting cellular stress, aging and cancer." (PMID 24116170, 2013). "The lack of these cancer stem cell markers, specifically SEMA5A (semaphorin 5A), KITL (KIT ligand, stem cell factor), CAV2 (caveolin 2), EPS8 (epidermal growth factor receptor pathway substrate 8) and PKP4 (plakophilin 4), was associated with acquired resistance to radiation in this study." (PMID 33767581, 2021).
infection (36 papers, 2006 to 2025). The state of being infected such as from the introduction of a foreign agent such as serum, vaccine, antigenic substance or organism. "The local increase in mast cell number at the site of infection mediated by the c-kit ligand SCF amplifies mast cell-mediated immune response." (PMID 38239615, 2023). "In this study, we showed that KITLG expression was significantly suppressed after infection with miR-34c, and the miR-34c-induced down-regulation of KITLG inhibited proliferation but promoted apoptosis in CRC cells that concomitantly express c-KIT and KITLG." (PMID 25213795, 2014). "Notably, however, transcripts for the hemopoietins stem cell factor (SCF, also known as Kit-ligand or Steel factor), granulocyte colony-stimulating factor (G-CSF), and interleukin-6 (IL-6) were significantly reduced upon infection of BM stroma." (PMID 27540380, 2016). "Downregulation of KITLG may inhibit cell migration and stem cell hemtopoiesis during the whole infection process." (PMID 21172007, 2010). "Activated mast cells release SCF, the KIT ligand, which recruits more mast cells to sites of allergen infiltration and infection." (PMID 23185384, 2012). "LMO2 was not indicated as modulated by TashAT2 in our RNA-Seq analysis due to variance in one control line and KITLG was not identified as modulated by infection in the TBL20/BL20 dataset." (PMID 37276213, 2023). "Data indicated that CRNG significantly increase KITLG, FOXP3 and miR-451, and decrease ANPEP and STAT5A mRNA expression, suggesting that CRNG may be necessary for the modulation of antiviral immunity, inflammation and pathogen infection." (PMID 31178726, 2019). "Moreover, microarray assay in combination with CRNG interference and overexpression showed that the differential genes such as ANPEP, KITLG, STAT5A, FOXP3, miR-451, IL-2, IL-10, IL-6, and TNF-α are mainly involved in viral and pathogens infection and the immune-inflammatory responses in PK-15 cells." (PMID 31178726, 2019). "Besides, Sta5a and Sta5b mediate cellular responses to the cytokine KITLG/SCF and other growth factors, which might help to fight against infection." (PMID 28977969, 2017).
KITLG also shares sentences with these, for which no sentence is quoted: leukemia (21 papers); mastocytosis (17); Constipation (13); COVID-19 (12); cervical cancer (9); small cell lung carcinoma (8); cardiovascular disease (6); depression (6); ischemia (6); psoriasis (6); acute myeloid leukemia (5); allergic asthma (5); Arthritis (5); Azoospermia (5); Cirrhosis (5); Cognitive impairment (5); hepatocellular carcinoma (5); inflammatory bowel disease (5); ischemic stroke (5); liver disease (5); liver fibrosis (5); metabolic syndrome (5); myeloid leukaemia (5); Obesity (5); Sepsis (5); allergic rhinitis (4); Alzheimer disease (4); atopic dermatitis (4); cognitive decline (4); colitis (4).
A further 231 diseases each share a sentence with KITLG in 4 papers or fewer.